RBP4 (retinol binding protein 4)
Diseases named in the same sentence as RBP4 in open-access papers (continued):
Sharing a sentence is not in itself a finding about the gene and the disease.
type 2 diabetes (continued). "The lipocalin retinol binding protein 4 (RBP4) has recently been reported to be a marker for abdominal fat mass in humans and some studies have suggested a role for RBP4 in the pathogenesis of type 2 diabetes." (PMID 18721461, 2008). "Indeed, it has been suggested that RBP4 may contribute to DKD by decreasing insulin sensitivity in both type 2 diabetes and obesity by promoting a pro-inflammatory response in adipose tissue." (PMID 38791060, 2024). "This study aimed to evaluate the effect of shift work on type 2 diabetes (T2DM) and Retinol binding protein 4 (RBP4) level." (PMID 37312059, 2023). "However, some reports do not support an association between RBP4 level and development of type 2 diabetes." (PMID 31690939, 2020). "In addition, the cubic spline regression analysis using variables from the model 2 suggested that the relationship between RBP4 and type 2 diabetes risk was linear and the P-nonlinearity value was 0.40 in men and 0.18 in women." (PMID 30651745, 2019). "In addition, elevated RBP4 levels have been observed in humans with obesity and/or type 2 diabetes." (PMID 30651745, 2019). "Since we measured RBP4 only once, some random measurement errors may exist, which could lead to non-differential misclassification of type 2 diabetes status and an underestimation of the true association." (PMID 30651745, 2019). "We observed a strong, dose-dependent association between plasma RBP4 levels and increased risk of incident type 2 diabetes in Chinese women but not men in our study, and confirmed this finding in a meta-analysis that further included two previous prospective studies." (PMID 30651745, 2019). "Lowering RBP4 could be a new strategy for treating type 2 diabetes with DR." (PMID 30135138, 2018). "Interestingly, anthocyanin (e.g., cyanidin-3-O-glucoside) have been shown to downregulate the RBP4 in the white adipose tissue in type 2 diabetic mice while at the same time upregulating the GLUT-4 and suppressed adipocytokines (monocyte chemoattractant protein-1 and tumor necrosis factor-α)." (PMID 29023424, 2017). "In type 2 diabetes mellitus (T2DM), vascular complications are mainly due to prolonged exposure to hyperglycemia clustering with other diseases such as hypertension and dyslipidemia and other risk factors including retinol-binding protein-4 and hypoxia-induced factor 1α." (PMID 25964115, 2015). "In addition, some adipocytokines, such as adiponectin or retinol-binding protein 4, may also contribute to the development of dyslipidaemia in patients with type 2 diabetes." (PMID 25725623, 2015). "More recently, retinol binding protein-4 (RBP4), an adipocytokine linked to insulin resistant states in mouse animal models and in humans and predicting the development of type 2 diabetes, has been associated to endothelial dysfunction in new-onset type 2 diabetes." (PMID 22938533, 2012). "None of the selected SNPs in GLUT4 or RBP4 showed any significant association with type 2 diabetes." (PMID 20625434, 2010). "Despite mechanistic studies linking retinol and RBP4 (retinol binding protein 4) to the pathogenesis of cardiovascular diseases (CVD) and type 2 diabetes (T2D), epidemiological evidence is still conflicting." (PMID 36017698, 2022). "Mechanistic studies suggested that retinol and RBP4 are involved in the pathogenesis of adverse cardiometabolic outcomes such as cardiovascular diseases (CVD) and type 2 diabetes (T2D)." (PMID 36017698, 2022). "In patients with type 2 diabetes, microalbuminuria and glomerular filtration rate (GFR) are independent determinants of elevated serum RBP4 levels." (PMID 35309061, 2022). "Previously, positive correlations were shown between RBP4 and triglyceride, total cholesterol, and LDL-C levels in type 2 diabetic patients." (PMID 34575030, 2021). "Retinol binding protein 4 (RBP4), a recently identified adipokine, has been introduced as a predictor for the onset of diabetes type 2 in coming future." (PMID 31953481, 2020).
type 2 diabetes (continued). "Student’s t-test, Pearson’s correlation and logistic regression analysis were used to evaluate the relationships between RBP4, TTR and type 2 diabetes markers." (PMID 29747616, 2018). "Levels of retinol-binding protein 4 (RBP4), an adipokine secreted by adipocytes and the liver, are elevated in type 2 diabetes." (PMID 25725623, 2015). "Based on the present findings and previous reports, RBP4 is thought to increase RLP-TG through the activation of RXR, inducing the overexpression of apoC-III and decreasing LPL activity in type 2 diabetic patients." (PMID 23671852, 2013). "Interestingly, OGTT 2-h plasma glucose concentrations had a more robust association with RBP4 levels than fasting plasma glucose concentrations, which might suggest OGTT 2-h plasma glucose as one main contribution through which increased RBP4 levels confer a higher risk of type 2 diabetes." (PMID 35634496, 2022). "RBP4 expression was selectively enhanced in adipose tissue in animal models of type 2 diabetes, but not in the liver." (PMID 29286303, 2017). "RBP4-treated adipocytes displayed the same molecular defects in insulin signaling, mediated by the insulin receptor substrate (IRS) protein 1 and the MAP kinase, as adipocytes from patients with type 2 diabetes." (PMID 24604418, 2014). "In conclusion, the present study showed that serum levels of RBP4 or total and HMW adiponectin were not potential predictors of CIMT in type 2 diabetic patients who exposed to this risk factor at least for nine years." (PMID 23497488, 2012). "Lack of correlation between CIMT and RBP4 has also been reported in a recent published article performed on newly diagnosed un-treated type 2 diabetes." (PMID 23497488, 2012). "SNPs in both RBP4 and GLUT4 have not been analyzed in Indian population for their association with type 2 diabetes." (PMID 20625434, 2010). "Treatment with candesartan decreased RBP-4 and resistin levels and increased visfatin but no significant changes were observed with olmesartan treatment in overweight hypertensive patients with type 2 diabetes." (PMID 37512134, 2023). "Moreover, RBP4 levels have been related with in vivo evaluation of endothelial function in patients with type 2 diabetes, but such relation has not been explored so far in essential hypertension." (PMID 22938533, 2012). "In conclusion, the present study showed that serum levels of RBP4 or total and HMW adiponectin were not potential predictors of CIMT, which reflects vascular structural changes, in type 2 diabetic patients who exposed to this risk factor at least for nine years." (PMID 23497488, 2012). "None of the SNPs in RBP4 and GLUT4 showed any association with type 2 diabetes." (PMID 20625434, 2010). "In addition, residual confounding may exist in the use of self-reported height, weight and history of hypertension, and information on family history of type 2 diabetes and pharmacological therapy that may affect glucose and RBP4 levels was not collected." (PMID 30651745, 2019). "Moreover, a strong, independent, negative association has been reported between plasma RBP4 and VLDL catabolism in patients with type 2 diabetes, suggesting that RBP4 may be involved in the pathophysiology of hypertriglyceridaemia in type 2 diabetes." (PMID 25725623, 2015). "We also did not observe any significant association of SNPs in RBP4 but our haplotype analysis revealed that a common haplotype (H6 – CGGT in the order rs3758538, rs3758539, rs36014035 and rs34571439) is significantly associated with type 2 diabetes (P = 0.004)." (PMID 20625434, 2010). "However, in this study, we did not observe any significant association of SNPs in RBP4 and STRA6 with diabetic retinopathy in a case control analysis using 155 samples with diabetic retinopathy and 150 samples with type 2 diabetes for more than 12 years with no symptoms of diabetic retinopathy." (PMID 20625434, 2010).
type 2 diabetes (continued). "At variance with that reported in patients with type 2 diabetes, RBP4 levels were not related to FMD in hypertensive individuals carrying endothelial dysfunction; similarly, E-selectin did not correlate with RBP4 in these patients." (PMID 22938533, 2012). "The aim of this study was to investigate whether carotid intima media thickness (CIMT) is associated with serum level of retinol- binding protein-4 (RBP4) and total and high molecular weight (HMW) adiponectin in type 2 diabetes (T2DM) without clinical symptom of atherosclerotic disease." (PMID 23497488, 2012).
metabolic syndrome (104 papers, 2010 to 2026). A cluster of metabolic risk factors for CARDIOVASCULAR DISEASES and TYPE 2 DIABETES MELLITUS. "Recent studies showed that RBP4 levels in adipose and circulating tissue are associated with IR, dyslipidemia and T2DM and therefore linked to MASLD." (PMID 39138826, 2025). "High-intensity interval training decreases RBP4 levels and improves insulin sensitivity in metabolic syndrome, and weight loss through bariatric surgery also reduces RBP4 levels and improves metabolic outcomes." (PMID 40276651, 2025). "Many researchers found that the serum levels of RBP-4 are associated with risk of metabolic syndrome." (PMID 36742396, 2023). "RBP4 has previously been implicated as a biomarker for metabolic syndrome and cardiovascular disease." (PMID 37674727, 2023). "Studies have indicated that high serum RBP4 in HCC combined with metabolic syndrome patients were closely associated with poor prognosis." (PMID 33834191, 2021). "RBP4 levels are elevated in adiposity and shown positive association with traditional atherosclerotic factors such as dyslipidemia and insulin resistance." (PMID 34758835, 2021). "Retinol binding protein 4 (RBP-4), another mediator linked to the metabolic syndrome, has been reported to be elevated in IBD and inversely correlated with disease activity." (PMID 31234447, 2019). "Elevated plasma concentration of retinol binding protein 4 (RBP4) has recently emerged as a potential risk factor as a component of developing metabolic syndrome (MS)." (PMID 29524177, 2018). "Using a multilevel modeling approach, this study identified a genetic variant with potentially functional attributes in the promoter of the RBP4 gene to be associated with HDL-C dyslipidemia." (PMID 30497399, 2018). "The present study was designed to investigate the associations of plasma RBP4 levels with oxidative stress, inflammatory markers, and metabolic syndrome (MetS) in a Chinese population." (PMID 24559154, 2014). "Even though the cardiovascular risk associated with metabolic syndrome has been well established, few data exist concerning the relationship between RBP4 and lipoprotein remnants such as remnant-like particles triglyceride (RLP-TG)." (PMID 23671852, 2013). "There is evidences that confirmed an association of increased circulating RBP4 levels and the metabolic syndrome." (PMID 24330836, 2013). "A recent study with dyslipidemia subjects found that circulating RBP4 concentrations were associated with small dense low-density lipoprotein (LDL) cholesterol and oxidized LDL levels." (PMID 23970879, 2013). "Elevated RBP4 levels were associated with a clustering of components of metabolic syndrome in insulin-resistant subjects." (PMID 23970879, 2013). "The influences of PPARγ (C1431T and Pro12Ala) and RBP4 (−803GA) polymorphisms on metabolic syndrome in HIV-infected patients receiving anti-retroviral therapy were examined in this study." (PMID 23145084, 2012). "PPARγ (C1431T and Pro12Ala) and RBP4 (−803GA) polymorphisms and metabolic syndrome among 91 HIV-infected patients." (PMID 23145084, 2012). "For example, a population study of men reported that RBP4 was associated with metabolic syndrome." (PMID 38520616, 2024). "RBP4 is associated with aging, metabolic syndromes, and cardiovascular diseases." (PMID 37510153, 2023). "Moreover, higher serum RBP4 levels were associated with an increased risk for prediabetes and metabolic syndrome in obese patients with NAFLD." (PMID 36009862, 2022). "Visceral fat expresses RBP4 at a higher level than subcutaneous fat, suggesting that RBP4 may be a marker for intra-abdominal fat accumulation, which is thought to exacerbate the underlying pathogenesis of metabolic syndrome." (PMID 35629362, 2022). "In addition, the primary vitamin A carrier in circulation, retinol-binding protein 4 (RBP4), has been related to cardiometabolic and inflammatory markers, and higher RBP4 concentrations are associated with metabolic syndrome and cardiovascular disease." (PMID 34741009, 2021).
metabolic syndrome (continued). "At the same time, elevated serum RBP-4 was associated with metabolic syndrome components." (PMID 34571734, 2021). "Notably, RBP4 and retinol were elevated in subjects with metabolic syndrome (p < 0.05), which was attributable to an association with elevated triglycerides (p = 0.013)." (PMID 31717719, 2019). "Elevated serum RBP4 levels were also associated with components of the metabolic syndrome." (PMID 30374329, 2018). "Therefore, the RBP4 is believed to be a potential biomarker for metabolic and cardiovascular disorders associated with dyslipidemia in the near future." (PMID 27103892, 2015). "Among these differentially expressed proteins, the RBP4 has been proposed as a major linkage between hypercholesterolemia, adipose tissues, liver and kidney, which is believed to be a potential biomarker for metabolic and cardiovascular disorders associated with dyslipidemia in the future." (PMID 27103892, 2015). "Among numerous secreted adipokines, some of them including nesfatin-1, retinol binding protein 4 (RBP4), omentin-1, vaspin, and progranulin, provide an extensive network of communication both within adipose tissue and are implicated directly in the pathologies associated with metabolic syndrome." (PMID 24330836, 2013). "However, it is the first study revealing the different effects of PPARγ and RBP4 polymorphisms on the metabolic syndrome after multivariate analysis adjusting for anti-retroviral drug, diet and drinking in HIV-infected patients receiving anti-retroviral therapy." (PMID 23145084, 2012). "In elderly, RBP4 concentrations were associated with Metabolic Syndrome (MetS) and its components in both genders, and prior cerebrovascular disease in men." (PMID 21869928, 2012). "In this article, we explored the relationships between the adipokines (visfatin and retinol binding protein 4 (RBP4)) and metabolic syndrome (MetS) components in both YDM and late-onset type 2 diabetes mellitus (ODM)." (PMID 37512089, 2023). "In general, elevated circulating and adipose tissue RBP4 levels have been correlated with IR, dyslipidemia, and T2DM." (PMID 36009862, 2022). "RBP4 and FABP4 are positively associated with metabolic syndrome, while APOD and LCN2 are ubiquitously expressed proteins with deleterious or beneficial effects, depending on their anatomical site of expression." (PMID 34638803, 2021). "Adipocytes and macrophages are further able to synthesize the retinol-binding protein 4 (RBP4); its levels are elevated under obese conditions and associated with features of the metabolic syndrome in humans." (PMID 33810619, 2021). "Other studies also have confirmed the relationship between the components of metabolic syndrome and RBP4 levels." (PMID 32718041, 2020). "Later on a new factor derived from fat cells, called retinol binding protein-4 (RBP-4) have been analyzed and shown to impair insulin sensitivity in the body and associated with various components of metabolic syndrome in diabetic subjects." (PMID 33133591, 2020). "This regulation has been under such scrutiny that recent studies have attempted to use RBP4 as an early marker of metabolic abnormalities including dyslipidemia." (PMID 30497399, 2018). "In line with a previous finding that resistin serum levels were significantly correlated with the inflammatory chemokines such as MCP-1 and RBP4, which are major players in the pathogenesis of metabolic syndromes." (PMID 29785210, 2018). "Regardless of which approach is the most appropriate, both studies identify RBP4 as a potential candidate for HDL-C dyslipidemia." (PMID 30497399, 2018). "This is consistent with our finding that the risk allele (C) of rs3758539, being associated with a lower expression of RBP4, confers a risk towards having HDL-C dyslipidemia." (PMID 30497399, 2018).